IL1B (interleukin 1 beta)
Diseases named in the same sentence as IL1B in open-access papers (continued):
Sharing a sentence is not in itself a finding about the gene and the disease.
infectious disease (67 papers, 2011 to 2025). A disorder directly resulting from the presence and activity of a microbial, viral, or parasitic agent in humans. "Though KEGG pathway classification, we observed that IL-1β-induced FLSs intervention was associated with the development of infectious diseases, the immune system, and cell growth and death." (PMID 38218854, 2024). "P2Y2R and P2X7R have been linked to IL-1β release in a caspase-1-dependent way during infectious diseases." (PMID 38239348, 2023). "Synthesis of IL-1β by platelets and IL-1β shedding in platelet MPs have been implicated in diverse pathologies including inflammatory, thromboembolic, and infectious diseases." (PMID 25814789, 2015). "Lower TLR-induced production of pro-IL-1β and IL-6 in innate immune cells during early infancy likely contributes to suboptimal vaccine responses and infectious diseases susceptibility." (PMID 24205068, 2013). "IL-1β is a cytokine that predicts inflammation, and the expression level of IL-1β increases considerably when various infectious diseases occur; in particular, the lung injury caused by smoking in the present experiment caused the expression level of IL-1β to increase by 10 times." (PMID 35892720, 2022). "Importantly, NLRP3 inflammasome-mediated IL-1β is required to drive an effective inflammatory response in infectious diseases triggered by pathogenic microorganisms." (PMID 32630207, 2020). "TNFα and IL-1β are the most important mediators of inflammation by gram-positive bacteria during infectious disease." (PMID 38234660, 2024). "Deficiencies in crucial cytokines, such as IL-6, IL-1β, and TNF-α, have been linked to severe infectious diseases." (PMID 38213288, 2024). "In vitro, macrophages with TET2-repressing mutations expressed the pro-inflammatory IL-1β, IL-6 and inflammasome NLRP3 in a pattern typically associated with macrophage activation in infectious diseases." (PMID 36835370, 2023). "Inflammasomes are signaling platforms that are activated in response to infectious diseases or chronic sterile inflammation and induce inflammation via triggering IL-1β and IL-18 or inducing pyroptosis via gasdermin-d (GSDMD)." (PMID 38026692, 2023). "High circulating IL-1β levels have been positively correlated with infectious disease severity (38, –, 40)." (PMID 37929965, 2023). "IL-1β affects the body’s innate and adaptive immunity through different mechanisms, so as to significantly enhance the body’s response to infectious diseases." (PMID 35409071, 2022). "As reported by existing studies, the IL-1β increased in atherosclerotic and infectious diseases, in which the inflammation have essential significance." (PMID 35155635, 2022). "Activation of these pathways can induce the production of pro-inflammatory factors such as IL-1β and IL-8 to regulate inflammatory and infectious diseases." (PMID 36120319, 2022). "IL-1β- and IL-8-related migration and activation of neutrophils reportedly had an important role in maintaining inflammation in M. bovis infectious diseases." (PMID 33863386, 2021). "IL-1β has been proposed to be an initiator of infectious diseases and is regarded as a proinflammatory signal." (PMID 34513006, 2021). "IL-1β is a key proinflammatory cytokine in pyroptosis, which played an important role in various infectious diseases." (PMID 32985562, 2020). "IL-1β is a pro-inflammatory cytokine which features in inflammatory and infectious diseases, leading immune cell recruitment and bacterial clearance eventually." (PMID 33128623, 2020). "Among many ways in which platelets can intermediate inflammatory and immune responses in infectious diseases recent evidence highlights the roles for inflammasome in platelets and the relevance of platelets as main sources of IL-1β." (PMID 25814789, 2015). "Contributions of platelet IL-1β synthesis and inflammasome activation to infectious diseases models are summarized here." (PMID 25814789, 2015).
infectious disease (continued). "Its levels are elevated in many inflammatory and infectious diseases including TB, and serum levels decline with treatment; its main role is the competitive inhibition of the inflammatory effects of IL-1α and IL-1β." (PMID 23691173, 2013). "ASEF-mediated enhancement of the priming step of inflammasomes might induce faster and more robust inflammatory responses (e.g., IL-1β secretion and pyroptosis) against invading pathogens in the host, effectively controlling infectious diseases." (PMID 38611734, 2024). "Although advanced studies have increased knowledge of alum as a vaccine adjuvant, research into the induction of a cellular response and biological function (e.g., IL-1β and neutrophil accumulation) is still vital for advancing its role in global vaccine development for infectious diseases." (PMID 35891284, 2022). "Nevertheless, it remains largely unclear how IL-1β and other related cytokines and chemokines are involved in the immunopathogenesis of CT; thus, more experiments are needed to provide further insights into this infectious disease." (PMID 29273062, 2017). "In addition, proinflammatory cytokines such as IL-1β are released in response to an infectious disease, while pleiotropic cytokines such as IFN-ω may be used to stimulate the immune response with a promising therapeutic effect." (PMID 41020892, 2025). "However, some reports demonstrated that the peritoneal macrophages express IL-18 precursor and usually activate during infectious diseases because most pathogens trigger the synthesis of mature IL-1β, which, in turn, activates caspase-1 to cleave pro-IL-18 to mature IL-18, which is then secreted." (PMID 36145686, 2022). "In the LPS-induced infectious disease model, there was a significant increase in chemokines (CCL2), proinflammatory cytokines (IL1β, IL6, TNFα), and a marked decrease in MCH." (PMID 38654385, 2024). "When NF-κB activity is inhibited, IL-1β and TNF-β can induce autophagy, thereby participating in the regulation of inflammation and infectious diseases." (PMID 35126598, 2022). "In order to show that EVs from GES-1 infected with H. pylori cells participate in the spread of infectious disease, the mRNA levels of proinflammatory cytokines TNF-α, IL-8, IL-6, IL-1β and IL-23, in GES-1 and AGS cells stimulated for 24 h with EVHp- or EVHp+ were measured by RT-qPCR." (PMID 36313672, 2022). "These physiological and pathological effects of IL-1β are dependent on its amount, and can be overridden with overproduction such as in infectious disease where IL-1β is believed to induce IR in non-immune tissue to deviate glucose-utilization to the immune cells." (PMID 37914804, 2023). "Importantly, it was found in other infectious disease models that caspase-11 is involved in induction of pyroptosis, alarmin as well as IL-1β secretion, in a process that is independent of the canonical activation of inflammasome." (PMID 32929083, 2020). "Thus, type I IFNs should be added to the long list of cytokines (IL-1β, IL-4, IL-6, IL-15, IL-21) and members of the tumor necrosis factor superfamily (TNFSF) (GITR-L, 4-1BB-L, OX40-L and TNF-α) that are purported to decrease Treg suppressive function in autoimmune and infectious disease models." (PMID 29672594, 2018).
psychiatric disorder (50 papers, 2011 to 2025). A disorder characterized by behavioral and/or psychological abnormalities, often accompanied by physical symptoms. "IL-1β is thought to be involved in microglial activation found in psychiatric disorders, but it has not been conclusively determined whether microglial activation may also be the cause of psychiatric disorders." (PMID 37589869, 2024). "Later, the axis of Alu-IL-18/IL-1β was activated and inflammation was triggered aggravating the progression and development of psychiatric disorders, in turn." (PMID 32038328, 2019). "Moreover, research on candidate genes and examine the impact of I IL-1β variations on psychiatric morbidity identified connections with various psychiatric disorders." (PMID 39841732, 2025). "A considerable body of evidence suggests that many neurological and psychiatric disorders are accompanied by disorders of IMs, like interleukin (IL)-1b, IL-2, IL-6, interferon (IFN), tumor necrosis factor a (TNF a), the soluble IL-6 receptor (sIL-6R), and the IL-1 receptor antagonist (IL-1RA)." (PMID 38674921, 2024). "However, regardless of prolonged antipsychotic treatment, we identified both a subgroup of cases with psychiatric disorders who displayed elevated inflammation and positive correlations between both IL1B and SERPINA3 mRNAs and lifetime antipsychotic dose." (PMID 34911938, 2021). "However, enhancement in the expression of IL-1β and IL-18 in psychiatric disorders by Alu is still unclear." (PMID 32038328, 2019). "Previous studies have demonstrated IL-1β is an important pro-inflammatory cytokine in the formation of psychiatric disorders: blocking IL-1β signaling with an antagonist greatly reduced inflammatory psychiatric disorders, and drugs targeting IL-1β are in phase II clinical trials." (PMID 30208926, 2018). "This subsequently reduces the level of pro-inflammatory factors, such as the cytokines TNF-α and IL-1β, chemokines, TLRs, and CRP, helping in alleviating both systemic and neuroinflammation, the latter being the causal factor for most psychiatric disorders." (PMID 24772064, 2014). "P2X7R may affect neuronal cell death through their ability to regulate the processing and release of IL-1β, a key mediator in neurodegeneration chronic inflammation, and, perhaps, some psychiatric diseases." (PMID 23940760, 2013). "It has been suggested that dysregulation of cytokines, particularly IL-1-β, IL-6, IL-10, interferon (IFN-γ), and TNF-α, contributes to the pathogenesis of certain psychiatric disorders." (PMID 37644934, 2023). "Genes of pro-inflammatory cytokines IL-1β, IL-6, and TNF were significantly upregulated in MSB macaques, which was similar to results from human psychiatric disorder studies." (PMID 34394017, 2021). "Central among these were cytokine signaling (e.g., IL‐1β, IL‐8) and dopaminergic transmission (DRD2, SLC6A3), underscoring the intricate crosstalk between the immune system and brain function in the pathophysiology of severe mental illness." (PMID 40922454, 2025). "Antidepressants are hypothesized to treat mental illness via immunoregulatory pathways, by decreasing levels of pro-inflammatory cytokines such as TNF52, IL-6, IL-1β, and IL-10." (PMID 39941688, 2025). "Inflammatory cytokines or other inflammatory stimuli (e.g., IL-1β, IL-4, IL-6, TNF-α, and MCP-1) induce depressive symptoms or other psychiatric disorders, and these factors may also predict the development of these disorders." (PMID 33536923, 2020). "The elevation of peripheral IL-1β, IL-6 and TNF-α could be a potential biomarker of vulnerability for psychiatric disorders in adults but their roles remain unknown for elderly." (PMID 30104698, 2018). "Previous studies noted higher blood levels of inflammatory biomarkers (including IL-6, IL-1β, TNF-α, and CRP) in people with mental illness who have suicidal attempts in comparison to healthy controls or non-suicidal people with mental illness." (PMID 39882160, 2024).
psychiatric disorder (continued). "Recently published systematic review and meta-analysis evaluated the peripheral levels of pro-inflammatory markers including IL-1β, IL-6, TNF-α, and CRP between the elderly with AD and controls without any psychiatric disorder." (PMID 31277647, 2019). "Moreover, our study included inflammatory markers that are not usually studied, including IL-1β, TNF-alpha, and adiponectin, while controlling for health risk-related behaviors (including physical inactivity) and performing a systematic assessment of comorbid psychiatric disorders." (PMID 31798472, 2019).
adenocarcinoma (40 papers, 2010 to 2026). A common cancer characterized by the presence of malignant glandular cells. "The TNF-α -238 A allele was associated with borderline higher odds of adenocarcinoma (OR 4.57, 95% CI: 0.95-21.95, p=0.050), while the *IL-1β* -511 T allele appeared protective (OR 0.45, 95% CI: 0.19-1.07, p=0.049)." (PMID 41727446, 2026). "In EGFR-mutant NSCLC, particularly adenocarcinomas, low IL-1β expression was associated with significantly improved OS." (PMID 40940992, 2025). "In KRAS-mutant adenocarcinoma, high IL-1β expression was associated with modestly longer TOT on immunotherapy (7.4 vs. 6.4 months; HR 1.15; p = 0.041), but not OS." (PMID 40940992, 2025). "Stratification analysis showed that IL-6 rs1800795 greatly increased the NSCLC risk in females and adenocarcinoma subtypes, whereas IL-1β rs16944 largely decreased the NSCLC risk for males, patients aged < 55, and nonsmokers." (PMID 38103126, 2024). "IL-1β is strong association with increased risk of GC, whereas ATP4b prompter-driven IL-1β Tg mice exhibited only 30% incidence of adenocarcinoma." (PMID 31141984, 2019). "We observed a significant upregulation of IDO1 mRNA in A549, H1792, H1838, H2347, HCC364 and HCC827 adenocarcinoma cell lines incubated with IL-1β." (PMID 37985999, 2023). "In adenocarcinomas without oncogenic mutations, high IL-1β was linked to improved OS (15.4 months in Q1 vs. 19.0 months in Q4; HR 1.15, 95% CI: 1.05–1.26, p = 0.003)." (PMID 40940992, 2025). "In NSCLC patients harboring KRAS mutations, IL-1β expression did not significantly affect OS in the overall population, adenocarcinoma or SCC subgroups." (PMID 40940992, 2025). "In addition, studies have shown that the overexpression of miR-223 in human adenocarcinoma alveolar basal epithelial cells can reduce LPS-induced Caspase-1, IL-1β, and IL-18 levels by targeting NLRP3." (PMID 38448875, 2024). "We observed three predominant macrophage states: an antigen-presenting C1QC+ state predominant in the normal colon, a pro-inflammatory IL1B+ state predominantly found in the normal liver, but also in normal colon and adenocarcinoma, and finally, a SPP1+ state enriched in tumors." (PMID 38036590, 2023). "Since both IDO1 and TDO2 can catalyze the conversion of Trp to Kyn, we asked whether IL-1β can also induce TDO2 expression in adenocarcinoma cells." (PMID 37985999, 2023). "Additionally, in esophagitis and Barrett's epithelium, the levels of pro-inflammatory cytokines IL-8 and IL-1β are high, and in adenocarcinoma, it is dramatically enhanced." (PMID 35511379, 2022). "Likewise, in a mouse model of esophageal carcinogenesis, IL-1β overexpression induced adenocarcinoma via activation of the NOTCH pathway." (PMID 33548281, 2021). "Long-term, IL-1β oversecretion leads to the organ atrophy and adenocarcinoma." (PMID 32630408, 2020). "Finally, to test the requirement of IL-1β in PM-enhanced adenocarcinoma formation, we initiated oncogene expression in the doxycycline-inducible CCSP-rtTa;TetO-EGFRL858R model and exposed mice to PM with concomitant administration of an anti-IL-1β or a control antibody (200 μg per dose)." (PMID 37020004, 2023). "This activation of the NF-κB pathway is paralleled by a simultaneous increase in interleukin (IL) IL-1β, IL-6, IL-8, and tumor necrosis factor (TNF) along the spectrum of reflux esophagitis, BE, and adenocarcinoma." (PMID 35511379, 2022). "Relevant to the BE pathology are IL1β and IL8 which have been shown to be increased during the stepwise progression from normal through Barrett’s epithelium to adenocarcinoma." (PMID 36233047, 2022). "Quercetin attenuated IL-1β-induced expression of ICAM-1 mRNA and protein in a dose-dependent manner in human A549 adenocarcinoma alveolar basal epithelial cells." (PMID 31064104, 2019). "4’-geranyloxy-ferulic acid and auraptene, both natural compounds isolated from plants, enhanced apoptosis in adenocarcinoma in AOM/DSS mice through suppression of NFκB, TNFα, NRF2, IL-6 and IL-1β." (PMID 31905803, 2019).
adenocarcinoma (continued). "Consistent with this, the expression of A3A – and to a lesser extent A3B, IL1A, and IL1B – was correlated with the squamous markers but not the adenocarcinoma markers in this dataset." (PMID 40323013, 2025). "Although it had no impact on the viability of adenocarcinoma cells, it significantly reduced IL-1β levels in the neoplastic microenvironment." (PMID 39519685, 2024). "Based on our findings, we now re-define the IL-1β transgenic mouse as a unique dual model that can be utilized to simultaneously study both inflammation-driven ESCC (plus oral SCC) and GEJ metaplasia/adenocarcinoma." (PMID 37543673, 2023). "In the present study, it was revealed that F. nucleatum could induce the production of proinflammatory cytokines (IL-8, IL-1β and TNF-α) and reactive oxygen species (ROS) in Caco-2 colorectal) adenocarcinoma cells." (PMID 27828984, 2016). "This specific model, validated for both germ-free and specific pathogen-free conditions, could provide nuanced insights into how apixaban might interact with IL-1β-mediated inflammation pathways and whether it has a role in halting or reversing the progression of SCC and adenocarcinoma." (PMID 39201414, 2024).